NKX1-2 (NK1 homeobox 2)
Description:
Transcriptional repressor. May play a role in early development as a Wnt/beta-catenin effector, hence controlling pluripotency and preimplantation development of embryonic stem cells. May promote adipogenesis in mesenchymal stem cells, possibly by inhibiting the expression of the antiadipogenic factor NR2F2. May inhibit osteoblastogenic differentiation.
Synonyms: C10orf121; bB238F13.2; NKX-1.1; SAX1
Tractability: No criterion of Open Targets' tractability assessment is met for any kind of drug.
Gene: Protein-coding gene on chromosome 10 (124,445,243 to 124,450,035, reverse strand). Ensembl gene ENSG00000229544.
Subcellular location: Nucleus; Nucleus, nucleolus
Subcellular location (Human Protein Atlas): Cytosol; Nucleoli fibrillar center
Gene Ontology:
Molecular function: DNA-binding transcription factor activity, RNA polymerase II-specific; RNA polymerase II cis-regulatory region sequence-specific DNA binding; DNA binding
Biological process: cell differentiation; regulation of transcription by RNA polymerase II; regulation of DNA-templated transcription
Cellular component: chromatin; nucleus; nucleolus
Genetic constraint (gnomAD): Loss-of-function variants: 1 observed, 5.3 expected, observed/expected ratio (o/e) 0.19, 90% interval 0.066 to 0.89. That is too few expected variants to judge how well the gene tolerates losing a copy. Missense variants: 503 observed, 327.52 expected, observed/expected ratio (o/e) 1.54, 90% interval 1.43 to 1.65. Synonymous variants: 235 observed, 162.42 expected, observed/expected ratio (o/e) 1.45, 90% interval 1.3 to 1.61.
Homologues: Orthologues: chimpanzee NKX1-2 (98% identical), macaque NKX1-2 (95% identical), pig NKX1-2 (80% identical), rabbit NKX1-2 (80% identical), dog NKX1-2 (78% identical), rat Nkx1-2 (72% identical), mouse Nkx1-2 (72% identical), zebrafish nkx1.2la (37% identical), tropical clawed frog nkx1-2 (30% identical), Drosophila melanogaster NK7.1 (22% identical), Caenorhabditis elegans cog-1 (17% identical), Drosophila melanogaster HGTX (17% identical), and 4 more. Paralogues in human: NKX1-1 (45% identical), NKX3-2 (22% identical), NKX6-1 (21% identical), NKX2-1 (20% identical), NKX2-4 (20% identical), NKX2-6 (20% identical), NKX2-3 (20% identical), NKX2-5 (19% identical), NKX2-2 (18% identical), NKX6-2 (18% identical), NKX3-1 (18% identical), NKX6-3 (17% identical), and 1 more.
Diseases named in the same sentence as NKX1-2 in open-access papers:
NKX1-2 is named in the same sentence as 3 diseases in open-access papers, as found by Europe PMC text mining. Sharing a sentence is not in itself a finding about the gene and the disease.
NKX1-2 shares sentences with these, for which no sentence is quoted: cancer (1 paper); deafness (1); embryonal carcinoma (1).